CTLA4 (cytotoxic T-lymphocyte associated protein 4)
Diseases named in the same sentence as CTLA4 in open-access papers (continued):
Sharing a sentence is not in itself a finding about the gene and the disease.
melanoma (continued). "In a retrospective analysis of two different trials of patients with melanoma treated with anti-CTLA-4 ± anti-PD1 ICI, HLA I expression was a reliable marker of response to anti-CTLA-4 ICI, but not to anti-PD1 ICI." (PMID 35585623, 2022). "Via inhibiting T cell cytotoxicity and facilitating melanomagenesis and progression in melanocytes and melanoma cells, upregulated CTLA-4 induced by IFN-γ was found to contribute to an immunosuppressive microenvironment." (PMID 35585975, 2022). "Our findings also revealed that high DCBLD2 expression levels were related to poorer PD1 outcomes in glioblastoma and melanoma, poorer CTLA4 outcomes in melanoma, and poorer PDL1 outcome in the bladder." (PMID 36034778, 2022). "The TIDE score has been shown to be more accurate than PD-L1 levels and TMB in predicting the therapeutic outcome of malignant melanoma patients treated with anti-PD-1 or anti-CTLA-4 antibodies." (PMID 35844514, 2022). "The p-value of the signature prediction for the OS of melanoma treated with CTLA4 is less than 0.05." (PMID 35924232, 2022). "In the absence of an STS cohort receiving immunotherapy, we introduced an independent melanoma dataset treated with the combination of anti-PD-1 and anti-CTLA-4." (PMID 35860263, 2022). "We also highlight a previously known locus (CTLA4) which is an immunotherapy target (anti-CTLA4 medication) in melanoma treatment." (PMID 36496446, 2022). "In 2018, a pooled analysis found an unexpected association between obesity (measured by body mass index; BMI) and better OS for anti‐CTLA4‐ or anti‐PD1/PDL1‐treated patients with advanced melanoma." (PMID 35394069, 2022). "As expected, urothelial carcinoma, renal cell carcinoma, and melanoma patients with high TIIClnc signature scores were prone to benefit more from anti-PD-1, anti-PD-L1, or anti-CTLA-4 immunotherapy, respectively." (PMID 35966587, 2022). "The first ICI approved by the U.S. Food and Drug administration (FDA) was ipilimumab (anti-cytolytic T lymphocyte Antigen 4 (CTLA-4) therapy) in 2011 after it was shown to prolong overall survival (OS) in advanced melanoma." (PMID 35585623, 2022). "For several malignancies, such as melanoma and non small-cell lung cancer, long-lasting durable responses have been achieved with CTLA-4 inhibitors such as ipilimumab and PD-1 inhibitors such as pembrolizumab." (PMID 35566403, 2022). "ICIs such as anti-PD1 Abs and anti-CTLA4 Abs have become anchor drugs in the treatment of advanced melanoma." (PMID 36555362, 2022). "The rationale is that this molecule is able to decrease hypoxia in the TME and is, therefore, able to re-sensitize melanoma tumors to anti-PD1 therapy in patients who have progressed on previous anti-PD1 therapy alone or in combination with anti-CTLA4 therapy." (PMID 35053435, 2022). "Melanoma patients who were treated with anti-CTLA-4, showed increased levels in the IL-17 producing CD4+ Th17 cells following treatment." (PMID 36713389, 2022). "Expression of PD-L1 on dendritic cells and macrophages in ovarian cancer and melanoma patients correlated with the efficacy of treatment with either anti-PD-1 alone or in combination with anti-CTLA-4." (PMID 35086548, 2022). "Bicarbonate administration has been shown to control Yumm1.1 melanoma growth and increase CD8+ T cell infiltration and NK and B cell activation, as well as improve anti-CTLA4 and anti–PD-1 therapy and adoptive cell therapy, in B16 melanoma–bearing mice." (PMID 35040434, 2022). "The use of PD-1 and CTLA-4 checkpoint inhibitors increased patient survival compared with traditional chemotherapy in a number of studies, including studies on kidney cancer, melanoma, head and neck squamous cell cancer (HNSCC) and non-small cell lung cancer." (PMID 36012588, 2022).
melanoma (continued). "Six patients had ICI therapy with a PD-1 inhibitor as first-line therapy, while two patients (melanoma) received combined ICI therapy with PD-1 plus CTLA-4 inhibitors (patient #1, 3); both of them showed a complete remission (CR) of the melanoma." (PMID 35936009, 2022). "Recent studies also identified associations between high TMB and clinical benefit in NSCLC, melanoma, and bladder cancer patients when treated with PD-1/PD-L1 inhibitors or CTLA4 blockade." (PMID 36006412, 2022). "And some related studies found that CTLA-4 blockade can dramatically improve overall survival in melanoma." (PMID 35757472, 2022). "CTLA-4 and PD-1 blockade improve the anti-tumor immune response amongst patients with melanoma, NSCLC, and hematological cancers, however, frequently with substantial adverse immunological effects." (PMID 35013519, 2022). "Biologics targeting PD-1, PD-L1, and CTLA-4 immune checkpoint proteins have been used in a variety of tumor types including small and non-small cell lung cancers, melanoma, and renal cell carcinoma." (PMID 35143542, 2022). "The TIDE database showed that the patients with high-expressed RAB42 had a better prognosis treated with PD1 or CTLA4 inhibitors in melanoma (dbGaP Study Accession: phs000452.v3.p1)." (PMID 36671428, 2022). "Systemic immunotherapies with Programmed Cell Death Protein 1 (PD-1) and Cytotoxic T-Lymphocyte-Associated Protein 4 (CTLA-4) inhibitors have improved the progression-free survival (PFS) and overall survival (OS) of patients with metastasized melanoma." (PMID 35158808, 2022). "Treatment with immune checkpoint inhibitors (ICIs) that target the programmed death 1 (PD-1) protein and the cytotoxic T-lymphocyte antigen 4 (CTLA-4) pathways drastically transformed the management of patients with advanced melanoma." (PMID 36654598, 2022). "TRIMs scores can relatively accurately predict the treatment effects with anti-PD-1 checkpoint inhibitor or CTLA-4 blockade in melanoma (AUC = 0.84 and 0.82)." (PMID 36461099, 2022). "Mechanisms by which tumor-intrinsic active β-catenin signaling results in T-cell exclusion and resistance to anti-PD-L1/anti-CTLA-4 monoclonal antibody therapy were discovered in an orthotopic mouse model of melanoma." (PMID 35965575, 2022). "The recombinant human immunoglobulin G1 and G2 monoclonal antibodies of CTLA-4, known as ipilimumab and tremelimumab, respectively, were trialed in melanoma and other advanced cancers, and both showed good efficacy." (PMID 35759331, 2022). "Treatment with anti-CTLA-4 was shown to broaden the peripheral TCR repertoire in melanoma patients, that differed for those with irAEs and those without." (PMID 36713389, 2022). "A meta-analysis of an scRNAseq dataset from melanoma patients treated with checkpoint inhibitors (anti-PD-1, anti-CTLA4 + anti-PD-1 or anti-CTLA4) revealed that TREM2high TAMs were 15.1-fold more abundant in non-responders." (PMID 35746551, 2022). "After this breakthrough, which revealed the anti-tumor potential of immune checkpoint blockade, hallmark clinical trials resulted in development of the anti-CTLA-4 monoclonal antibody, Ipilimumab, which was approved for treatment of melanoma in 2011." (PMID 36295867, 2022). "Anti‐PD‐1 and anti‐CTLA‐4 mAbs increased γδ T cell infiltration and killing of melanoma cells in all four models." (PMID 35731974, 2022). "More recently, another systematic review and meta-analysis estimated irAE in 6331 patients with advanced melanoma treated with anti-CTLA-4 or anti-PD-1 antibodies as monotherapy or in any concomitant or sequential combination." (PMID 36077430, 2022). "In the same vein, melanoma patients resistant to anti-CTLA-4 blockade showed high blood propionate and butyrate levels and higher proportion of Tregs." (PMID 35371048, 2022). "Inspired by the melanoma experience, double blockade of CTLA-4 and PD-1/PD-L1 is a promising combination regimen." (PMID 35883692, 2022).
melanoma (continued). "At least additive antitumor responses were seen in melanoma lung metastasis treated with anti-CTLA-4 and anti-CHI3L1 antibodies in combination." (PMID 36618349, 2022). "The study of pembrolizumab with ipilimumab as second-line therapy for advanced melanoma provided compelling evidence that the combination of PD-1 and CTLA4 is a safe and effective treatment approach in the PD-1–refractory patient population." (PMID 35456332, 2022). "High TMB (>100 nonsynonymous mutations per exome) and the presence of specific neoepitope signatures correlated with response to and survival with CTLA-4 inhibitors in a discovery set of 25 patients and a validation set of 39 patients with melanoma." (PMID 35703181, 2022). "We noted a significant stimulation of CTLA-4 and its ligands B7-1 and B7-2 in the lungs with melanoma metastasis." (PMID 36618349, 2022). "Chaput’s study also showed that in melanoma patients receiving anti-CTLA-4 treatment, different gut microbiota composition was related to the occurrence and development of IMC and clinical efficacy of ICIs." (PMID 36189293, 2022). "Each anti-CHI3L1 and anti-CTLA-4 antibody inhibited melanoma lung metastasis when compared to isotype controls." (PMID 36618349, 2022). "Currently, anti-PD-1 (nivolumab, pembrolizumab) and anti-CTLA4 (ipilimumab) antibodies are commonly used in the treatment of malignant melanoma." (PMID 35406444, 2022). "Ipilimumab, for use in advanced melanoma, was the first approved ICI in 2011, and is a drug that targets the cytotoxic T-lymphocyte-associated protein 4 (CTLA-4) checkpoint." (PMID 35453571, 2022). "Numerous successes have been achieved with anti-PD1, anti-CTLA4, or combination therapies in treating melanoma and other types of cancers." (PMID 36613491, 2022). "In patients treated for melanoma, the rate of LC appears to be higher when using anti-PD-1, with rates of 80–96% compared to anti-CTLA4, with rates of 16.5–100%." (PMID 35740435, 2022). "Clinical results demonstrated that anti-PD-1 mAbs were more successful than anti-CTLA4 mAbs in patients with advanced-stage melanoma." (PMID 35996120, 2022). "In vivo, GM-CSF cell-based vaccines (GVAX) plus anti-CTLA-4 antibody has shown synergistic impacts in attenuating tumor size and restoring the antitumor immune reactions in melanoma and also prostate mice model." (PMID 35392976, 2022). "In a recent investigation involving cancer immunotherapy, Bacteroides was determined to be required for the response to the CTLA4 blockade against melanoma/NSCLC in both human patients and murine models." (PMID 36429112, 2022). "In prior research, histone acetylation mediated by p300/CBP was found to be critical for the transcriptional activation of CTLA-4 licensed by interferon-gamma (IFN-γ) signaling in melanoma cells." (PMID 35585975, 2022). "Another T cell checkpoint, CTLA-4, is also expressed on cancer cells such as melanoma, leading to potential NK cell mediated ADCC against CTLA-4+ cancers induced by anti-CTLA-4 treatment." (PMID 35967421, 2022). "Some studies have found that the high levels of CTLA-4 correlate with better efficacy of anti-CTLA-4 therapies in melanoma." (PMID 35646659, 2022). "In another clinical study, 26 melanoma patients who received anti-CTLA4 Abs treatment were investigated; consequently, Faecalibacterium spp." (PMID 36429112, 2022). "The engagement of CTLA-4 on primary melanoma cell lines induces antibody-dependent cellular cytotoxicity and TNF-α production." (PMID 35493488, 2022). "The hazard ratio can be increased even in monotherapies for malignant melanoma (HR = 4.3 for anti-PD-1 and 4.93 for anti-CTLA-4)." (PMID 35433707, 2022). "At least additive antitumor effects were seen in the mice with melanoma lung metastasis treated simultaneously with individual antibodies against CTLA-4 and CHI3L1." (PMID 36618349, 2022).
melanoma (continued). "In recent years, immune checkpoint inhibitors (ICIs) targeting the programmed death-ligand 1 (PD-L1), cytotoxic T-lymphocyte antigen 4 (CTLA-4), and programmed cell death receptor 1 (PD-1) have revolutionized the treatment landscape for melanoma." (PMID 36733353, 2022). "A small clinical trial in melanoma patients investigated treatment of tretinoin at high dose during 4 days surrounding the dosing of either anti-CTLA4 or anti-PD1, which showed excellent tolerability." (PMID 35402250, 2022). "We used SubMap and a melanoma cohort treated with sequential CTLA-4 and PD-1 blockade to predict patients’ responses." (PMID 36311750, 2022). "Antibodies against CTLA-4 diminish tumor growth in murine neoplastic modeling systems and are effective as mono therapies in advanced melanoma, colorectal and renal cell cancers." (PMID 36618349, 2022). "Considering that melanoma CSCs also express PD-1 and PD-L1 and CTLA-4, in association with ALDH, consequently, anti-PD-L1 and/or anti-CTLA-4 combined with CSC-DC vaccine showed improved response." (PMID 35334544, 2022). "The ADCC mediated by TAMs was shown in a study where melanoma patients responders to ipilimumab (mAb anti-CTLA-4) had higher numbers of circulating CD16+ monocytes and macrophages at tumor sites and lower Treg cells." (PMID 35664746, 2022). "Immunotherapeutic agents such as anti-PD-1 (pembrolizumab and nivolumab) and anti-CTLA-4 (ipilimumab) have revolutionized melanoma treatment; however, drug resistance is rapidly acquired." (PMID 36135194, 2022). "Around 41% of patients with melanoma receiving a CTLA-4 inhibitor alone developed any grade of diarrhea, compared to 25% to 27% patients with lung cancer." (PMID 36612082, 2022). "Local radiation therapy combined with systemic anti-CTLA-4 prolonged PFS in patients with melanoma compared with that noted (4.4 months) in patients treated with ipilimumab alone." (PMID 35037899, 2022). "The discovery of immune checkpoints on T-cells, such as cytotoxic T-lymphocyte-associated antigen 4 (CTLA-4) or programmed cell death protein 1 (PD-1), and using them as therapeutic targets marked a breakthrough in melanoma treatment." (PMID 36428768, 2022). "In 2011, the FDA for the first time approved the use of the checkpoint inhibitor ipilimumab – a monoclonal antibody inhibiting CTLA-4 – as a frontline cancer treatment in advanced melanoma." (PMID 35078492, 2022). "Ipilimumab, an antibody that relieves the inhibition of cytotoxic T cells by targeting CTLA-4, has achieved “blockbuster” status, since its approval for melanoma and lung cancer in 2011." (PMID 35157702, 2022). "Treatment with DNMT inhibitors (DNMTis) in mouse models sensitizes melanoma cells to subsequent anti-CTLA4 therapy." (PMID 35887150, 2022). "Several studies have shown that patients with less heterogeneous melanoma responded better to the blocking action of anti-CTLA-4 and anti-PD1." (PMID 33917181, 2021). "Therapeutic antibodies targeting the immune inhibitory receptors Programmed Death-1 (PD-1) and Cytotoxic T Lymphocyte Antigen-4 (CTLA-4) induce durable responses in a proportion of patients with melanoma, lung, kidney, bladder and other cancers." (PMID 34201655, 2021). "We identified retrospectively N = 30 stage IV melanoma patients treated with single-agent anti-CTLA-4 immunotherapy (ipilimumab)." (PMID 33196890, 2021). "NK cells expressing CD28 and CTLA-4 were also identified in mouse RMA-S, melanoma, and lung tumors, and responded to CTLA-4 activation ex vivo with decreased IFN-γ production." (PMID 35082797, 2021). "A CTLA4 blockade using ipilimumab and tremelimumab prolongs the antitumor immune responses in melanoma and PCa patients." (PMID 34316327, 2021). "What is more, we performed subclass mapping to compare the expression profile of the high/low subgroups and another published dataset containing 47 patients with melanoma that responded to immune checkpoint inhibitors (CTLA-4 and PD-1)." (PMID 34124058, 2021).
melanoma (continued). "CTLA4, a negative regulator of T-cell activation, was approved as the first immune checkpoint in melanoma treatment and anti-CTLA4 immunotherapy has shown outstanding antitumor efficacy in clinical trials of ovarian cancer patients." (PMID 34094977, 2021). "Immune checkpoint blockade therapy, including anti-PD1, anti-PDL1, and anti-CTLA-4, has been proven to improve the overall survival of patients with advanced melanoma." (PMID 34025664, 2021). "Among the melanoma patient cohort who received anti-CTLA-4 checkpoint blockade therapy, we observed a reduction in the gene expression level of NLRC5-dependent MHC class I and CD8+ T cell genes in non-responders versus responders." (PMID 33547395, 2021). "The first FDA (United States Food and Drug Administration) approval granted for any ICI was for an anti-CTLA-4-targeting monoclonal antibody, ipilimumab, for melanoma in 2011 after showing a survival benefit in patients with pre-treated metastatic disease." (PMID 34298632, 2021). "We also confirmed the predictive value of HSPA7 in a cohort of melanoma patients who received anti-CTLA4 therapy and an IMvigor210 cohort of patients treated with anti-PD-L1 therapy." (PMID 34354698, 2021). "Nivolumab, an anti-programmed death-1 (PD-1) antibody, and ipilimumab, an anti-cytotoxic T-lymphocyte associated-protein 4 (CTLA-4) antibody, have led to improvements in survival when used in stage III and IV melanoma patients." (PMID 34976006, 2021). "If we consider the systemic treatment administered (anti-PD-1 vs. anti-CTLA4), a higher LC was observed in patients with melanoma when anti-PD-1 was used with rates of 80–96% versus anti-CTLA4 with rates of 16.5–100%." (PMID 34769050, 2021). "CTLA-4 expression by melanoma cells was heterogeneous, e.g., tumors with predominantly CTLA-4-negative tumor cells, tumors with mainly weakly CTLA-4-expressing tumor cells, and melanomas with strongly CTLA-4-expressing tumor cells." (PMID 33196890, 2021). "These preclinical lines of evidence highlight the possible synergy of combined targeting of CTLA-4 and PD-1, which has been demonstrated clinically in several solid tumors including melanoma and others." (PMID 32601377, 2021). "Data obtained in clinical trials of ipilimumab (anti-CTLA-4) were the basis for approval of the drug in 2011 by the FDA in patients with clinically advanced melanoma." (PMID 34236546, 2021). "It has been reported that pretreatment with pan-HDAC inhibitors such as AR42 and sodium valproate enhances the therapeutic efficacy of anti-PD-1 and anti-CTLA-4 antibodies in B16 mouse melanoma models." (PMID 34944799, 2021). "The monoclonal antibodies developed for PD‐1 and its ligands as well as CTLA4 have been approved for the clinical therapy of several cancers (eg melanoma and non‐small‐cell lung carcinoma)." (PMID 34523782, 2021). "Several clinical trials have been conducted to combine vaccination with anti-CTLA-4 in melanoma patients using peptide vaccines." (PMID 34830973, 2021). "Studies have recently demonstrated that treatment with ipilimumab (anti-CTLA4) in melanoma patients decreased numbers of both M- and PMN-MDSC and this correlated with favourable therapeutic effects." (PMID 34885021, 2021). "Recently, immune checkpoint blockade with antibodies targeting CTLA-4 and PD-1/PD-L1 has become an important treatment strategy for melanoma patients." (PMID 34221994, 2021). "Accordingly, improved clinical responses were observed in patients with stage II and stage III melanomas treated with the anti-CTLA4 Tremelimumab combined with high-dose IFN-α2b." (PMID 34571733, 2021). "This is thought to be the result of a type I IFN response that was induced by Azacytidine as the presence of this type I IFN gene signature is predictive for response to CTLA-4 blockade in melanoma patients." (PMID 33859645, 2021). "Severe hypophysitis is observed in 5% of melanoma patients treated with ipilimumab but is rare in CTLA4+/- patients (1 of 133)." (PMID 35154081, 2021).